ANGPTL4 (angiopoietin like 4)
Description:
Mediates inactivation of the lipoprotein lipase LPL, and thereby plays a role in the regulation of triglyceride clearance from the blood serum and in lipid metabolism. May also play a role in regulating glucose homeostasis and insulin sensitivity (Probable). Inhibits proliferation, migration, and tubule formation of endothelial cells and reduces vascular leakage. Upon heterologous expression, inhibits the adhesion of endothelial cell to the extracellular matrix (ECM), and inhibits the reorganization of the actin cytoskeleton, formation of actin stress fibers and focal adhesions in endothelial cells that have adhered to ANGPTL4-containing ECM (in vitro). Depending on context, may modulate tumor-related angiogenesis (By similarity). [ANGPTL4 N-terminal chain]: Mediates inactivation of the lipoprotein lipase LPL, and thereby plays an important role in the regulation of triglyceride clearance from the blood serum and in lipid metabolism. Has higher activity in LPL inactivation than the uncleaved protein.
Synonyms: HFARP; ARP4; PGAR; PP1158; FIAF; NL2; HARP; TGQTL; UNQ171
Tractability: Small molecule: a structure with a bound ligand is known. Antibody: UniProt places it where antibodies can reach, with high confidence; its Gene Ontology location is reachable by antibodies, with high confidence; UniProt predicts a signal peptide or a membrane-spanning region. PROTAC: its protein half-life has been measured.
Gene: Protein-coding gene on chromosome 19 (8,363,223 to 8,374,371, forward strand). Ensembl gene ENSG00000167772.
Subcellular location: Secreted; Secreted, extracellular space, extracellular matrix
Subcellular location (Human Protein Atlas): Nucleoplasm; Vesicles; Predicted to be secreted
Pathways (Reactome):
Cell-Cell communication: Regulation of CDH11 function
Developmental Biology: Transcriptional regulation of white adipocyte differentiation
Gene expression (Transcription): MLL4 and MLL3 complexes regulate expression of PPARG target genes in adipogenesis and hepatic steatosis
Metabolism: PPARA activates gene expression
Transport of small molecules: Assembly of active LPL and LIPC lipase complexes
Gene Ontology:
Molecular function: identical protein binding; lipase binding; lipase inhibitor activity; protein binding; enzyme inhibitor activity
Biological process: negative regulation of apoptotic process; negative regulation of fatty acid biosynthetic process; negative regulation of very-low-density lipoprotein particle remodeling; protein unfolding; regulation of chylomicron remodeling; regulation of triglyceride transport; positive regulation of angiogenesis; response to hypoxia; triglyceride homeostasis; blood coagulation; positive regulation of multicellular organismal process
Cellular component: blood microparticle; extracellular region; extracellular matrix
Genetic constraint (gnomAD): Loss-of-function variants: 41 observed, 35.93 expected, observed/expected ratio (o/e) 1.14, 90% interval 0.89 to 1.48. The upper end of that interval is the gene's LOEUF score, 1.48, which puts it in group 6 of 6, group 1 being the genes least tolerant of losing a copy. Missense variants: 545 observed, 519.8 expected, observed/expected ratio (o/e) 1.05, 90% interval 0.98 to 1.12. Synonymous variants: 233 observed, 210.93 expected, observed/expected ratio (o/e) 1.1, 90% interval 0.99 to 1.23.
Homologues: Orthologues: chimpanzee ANGPTL4 (99% identical), macaque ANGPTL4 (95% identical), rabbit ANGPTL4 (82% identical), pig ANGPTL4 (81% identical), dog ANGPTL4 (79% identical), rat Angptl4 (76% identical), mouse Angptl4 (75% identical), guinea pig ANGPTL4 (70% identical), zebrafish angptl4 (41% identical), tropical clawed frog angptl4 (40% identical). Paralogues in human: ANGPTL3 (31% identical), ANGPTL1 (26% identical), ANGPTL6 (26% identical), FGG (26% identical), ANGPT1 (25% identical), ANGPTL2 (25% identical), ANGPT4 (24% identical), ANGPT2 (23% identical), TNXB (23% identical), TNR (23% identical), ANGPTL7 (23% identical), TNC (23% identical), and 13 more.
Diseases named in the same sentence as ANGPTL4 in open-access papers:
ANGPTL4 is named in the same sentence as 301 diseases in open-access papers, as found by Europe PMC text mining. Sharing a sentence is not in itself a finding about the gene and the disease. The quoted sentences say what the papers report.
breast cancer (106 papers, 2008 to 2025). A primary or metastatic malignant neoplasm involving the breast. "On the other hand, subgrouping resolved heterogeneity in the breast cancer subgroup, and results show a significant association between ANGPTL4 expression and worse OS (HR = 1.59, 95% CI: 1.32–1.90)." (PMID 40233044, 2025). "ANGPTL4 expression has been associated with a worse prognosis in cervical cancer, gallbladder cancer, breast cancer, and pancreatic cancer." (PMID 40233044, 2025). "Further data mining of the starBase database for breast cancer (BRCA) samples demonstrated FTO expression negatively associated with ANGPTL4 expression." (PMID 39910592, 2025). "Angiopoietin-like 4 (ANGPTL4) is an important TGFβ downstream factor and is associated with the prognosis of breast cancer." (PMID 38245723, 2024). "For example, methylation and downregulation of ANGPTL4 are associated with progression and metastasis in colon cancer but overexpression is associated with progression and poor prognosis in breast cancer." (PMID 37291514, 2023). "High ANGPTL4 expression was associated with pathological stage and shorter overall survival and disease-free survival in patients with breast cancer." (PMID 36147494, 2022). "Overexpression of ANGPTL4 is associated with lower disease‐free survival in young breast cancer patients." (PMID 36074318, 2022). "In breast cancer, full-length ANGPTL4 was associated with lower relapse and vascular invasion rates and overexpression of full-length ANGPTL4 inhibited breast cancer cell adhesion and attachment, which lead to inhibition of cell invasion and migration." (PMID 35463073, 2022). "Although emerging studies have implicated that ANGPTL4 plays an essential role in tumor-associated activities, it is associated with multiple cancers, such as papillary thyroid cancer, breast cancer, and cutaneous melanoma." (PMID 34876931, 2021). "In our study, we found that a positive serum concentration of ANGPTL4 over 0.1 ng/mL was associated with an increased risk of brain metastasis in women with breast cancer, and with shorter survival." (PMID 32405335, 2020). "Multivariate analyses according to type of cancer and metastatic localization found that only breast cancer brain metastases were significantly associated with elevated ANGPTL4 serum concentration (p < 0.05)." (PMID 32405335, 2020). "These four variables were also selected in the breast cancer mortality model, in addition to ANGPTL4, a VEGF-13 marker implicated in angiogenesis, and SPINT1, a claudin-low feature involved in epithelial cell differentiation." (PMID 31542876, 2020). "In summary, we found that positive ANGPTL4 serum concentration over 0.1 ng/mL was associated with an increased risk of brain metastases and shorter survival in patients with breast cancer." (PMID 32405335, 2020). "Multivariate analyses found that only breast cancer brain metastases were significantly associated with elevated ANGPTL4 serum concentrations." (PMID 32405335, 2020). "We recently showed that obesity-associated inflammation promotes the upregulation of ANGPTL4 in adipocytes, which drives breast cancer angiogenesis and progression." (PMID 32630445, 2020). "In a preclinical murine model of brain metastases using human breast cancer cell lines, ANGPTL4 mRNA and protein expression were associated with an increased risk of lung and brain metastases." (PMID 32405335, 2020). "For breast cancer patients, a significant association was systematically found between positivity of ANGPTL4 serum concentration and brain metastasis, whatever the level of positivity for ANGPTL4 serum concentration (p < 0.01)." (PMID 32405335, 2020). "Angiopoietin-like 4 is part of gene signatures associated with distant metastasis and tumour aggressiveness in breast cancer and is overexpressed in high-grade breast carcinoma." (PMID 28458654, 2017).
breast cancer (continued). "High expression of ANGPTL4 in primary breast tumors is strongly associated with metastasis to the lung and has also been implicated in brain metastasis in breast cancer." (PMID 25999348, 2015). "Furthermore, cancer-associated fibroblasts (CAFs) secrete ANGPTL4 as a mediator to promote breast cancer and prostate cancer progression." (PMID 40616161, 2025). "Moreover, Kaplan–Meier survival analysis of patient specimens revealed that high ANGPTL4 expression was associated with poorer overall survival, particularly in patients with basal-like breast cancer." (PMID 40616161, 2025). "Additionally, STAT3 activation in cancer-associated fibroblasts increases the secretion of ANGPTL4 into the tumor microenvironment, promoting breast cancer progression in vivo and enhancing invasion and migration in breast cancer cells." (PMID 40723247, 2025). "Breast cancers of the triple negative subtype may be different since ANGPTL4 overexpression in that context has been associated with inhibition of invasion." (PMID 37291514, 2023). "HIF signaling plays a role in cell extravasation by affecting the expression of the gene that encodes for L1 cell adhesion molecule involved in breast cancer cell adhesion to endothelial cells, as well as ANGPTL4 coding for angiopoietin-like 4 that decreases adhesion between endothelial cells." (PMID 36139678, 2022). "A hypoxic profile that included 13 genes such as VEGF and ANGPTL4, has been associated with distant metastases and might represent an independent predictor of outcomes in primary breast cancers." (PMID 20454689, 2010). "ANGPTL4 has been shown to promote the pro-tumorigenic effect of CAFs in a murine model of breast cancer by inducing STAT3, a transcription factor known for its role in EMT, angiogenesis, and inhibiting apoptosis." (PMID 40233044, 2025). "For instance, ANGPTL4 is upregulated in several cancers, including renal cell carcinoma, breast cancer, and colorectal cancer." (PMID 40723247, 2025). "In breast cancer, overexpression of ANGPTL4 correlates with tumor progression and increased malignancy, and patients with higher ANGPTL4 expression tend to have a worse overall prognosis." (PMID 40723247, 2025). "In breast cancer lung metastasis models, angiopoietin-like 4 (ANGPTL4) secreted by pulmonary stromal cells impairs ATGL function in neutrophils, thereby promoting intracellular triglyceride storage." (PMID 40564191, 2025). "Using the breast cancer online database bc-GenExMiner, box plots indicated that ANGPTL4 expression at the RNA level was significantly elevated in basal-like and TNBC subtypes." (PMID 39910592, 2025). "In survival analysis, breast cancer patients with elevated ANGPTL4 or KLF4 protein levels had poorer overall survival relative to those with low ANGPTL4 or KLF4 expression." (PMID 40616161, 2025). "Ultimately, our objective was to examine the correlation between fibroblast cell markers, notably CFD and ANGPTL4, and the prognosis of breast cancer patients." (PMID 40340806, 2025). "Our findings highlight the critical role of ANGPTL4 in driving tumor progression within the framework of adipocyte-accelerated breast cancer." (PMID 40616161, 2025). "Other studies have found that ANGPTL4 can promote angiogenesis in various pathological conditions, including arthritis, renal cell carcinoma, and breast cancer." (PMID 40723247, 2025). "Functionally, ANGPTL4 destroys the connections between vascular endothelial cells, enhancing the entering of breast cancer cells into the lung parenchyma." (PMID 38245723, 2024). "ANGPTL4 can promote the development and progression of multiple cancer types, including breast cancer, pancreatic cancer, glioblastoma and colon cancer." (PMID 38212795, 2024). "Previous reports indicated that TGF-β primed breast cancer for lung metastasis seeding and brain metastasis via ANGPTL4." (PMID 38643448, 2024).
breast cancer (continued). "Multiple studies have indicated that ANGPTL4 is a functionally complex protein in many types of cancer, including gastric cancer, OC, colon cancer, and breast cancer." (PMID 38212795, 2024). "The increased expression of ANGPTL4 observed in tumor cells at the invasive front in the overweight/obese group now provides novel in vivo evidence supporting a role for ANGPTL4 in obesity-related breast cancer." (PMID 39456610, 2024). "Recent investigations have provided evidence of FABP4, CD36, and ANGPTL4, proteins involved in the release, uptake, and intracellular handling of triglycerides and fatty acids, in breast cancer pathology." (PMID 39456610, 2024). "In some cancers, the ANGPTL4 expression promoted venous invasion and cancer progression in breast cancer, thyroid cancer, colorectal cancer and gastric cancer, and was associated with a poor prognosis in breast cancer." (PMID 37938151, 2023). "Culture of MCF0742 (breast cancer) and UACC501516 (melanoma) cells in the presence of GW0742 caused upregulation of the PPARβ/δ target gene angiopoietin-like protein 4 (ANGPTL4), and the growth of both tumor cell lines was inhibited." (PMID 37251321, 2023). "In this way, adipocyte-secreted ANGPTL4 promoted angiogenesis and breast cancer progression in obese mice." (PMID 36670988, 2023). "Previous studies have confirmed the high expression of ANGPTL4 in a variety of malignant tumor cells and tissues, such as pancreatic cancer, gastric cancer, cholangiocarcinoma cells, and breast cancer." (PMID 36467503, 2022). "The purpose of the current study was to investigate the protein expression of ANGPTL4 and IGF-1 in primary breast carcinoma tissue and its association with breast cancer molecular subtypes in patients younger than 45 years." (PMID 35366286, 2022). "RAB11B-AS1 enhances hypoxia-induced VEGFA and ANGPTL4 expression in breast cancer and promotes angiogenesis and distant breast cancer metastasis in mice." (PMID 36139678, 2022). "ANGPTL4 is highly expressed in breast cancer, colorectal cancer, prostate cancer, liver cancer, kidney cancer and other tumours and participates in the regulation of tumour growth, redox reactions, angiogenesis, metastasis and other biological functions." (PMID 35285130, 2022). "Accordingly, ANGPTL4 was reported to promote venous invasion and distant spread in colorectal and renal cell cancer, as well as in gastric and breast cancer." (PMID 36074318, 2022). "Rab11b-as1 enhances the expression of angiogenic factors including VEGFA and ANGPTL4 in hypoxia breast cancer cells by increasing the recruitment of RNA polymerase II, promoting tumor angiogenesis and distant metastasis of breast cancer in vitro." (PMID 36226050, 2022). "Although studies have shown that the high expression of ANGPTL4 in breast cancer is beneficial to inhibit the proliferation of triple‐negative breast cancer, more studies have shown that ANGPTL4 has a significant effect on lung cancer cell proliferation." (PMID 35285130, 2022). "Expression of ANGPTL4 in breast cancer was enhanced by lncRNA RAB11B-AS1 through increasing recruitment of RNA polymerase II in response to hypoxia, then promoted cancer invasion and distant metastasis." (PMID 36050447, 2022). "Adipocyte-derived ANGPTL4 was beneficial to breast cancer angiogenesis and progression in obesity and was a potential therapeutic target for obese breast cancer patients." (PMID 35701840, 2022). "While L1CAM increases the adherence of breast cancer cells to EC monolayers via hemophilic or heterophilic interactions, ANGPTL4 blocks EC−EC interactions, facilitating the vascular metastasis of breast cancer cells to the lung parenchyma." (PMID 36551540, 2022). "In the serum of 113 patients with different types of cancers, we initially assessed ANGPTL4 concentrations and showed that ANGPTL4 was elevated in women with breast cancer brain metastases." (PMID 32405335, 2020).
breast cancer (continued). "Using an experimental murine model of breast cancer brain metastases, we investigated the role of each cleaved fragment of ANGPTL4 in the occurrence of brain metastases." (PMID 32405335, 2020). "In this sub-group of 38 women with breast cancer, the mean ANGPTL4 serum concentration was 5.6 ng/mL, ranging from 0 to 52.8 ng/mL." (PMID 32405335, 2020). "It was also reported that the blockage of HIF-mediated ANGPTL4 inhibits vascular metastasis of breast cancer cells to the lungs." (PMID 31963541, 2020). "ANGPTL4 had been identified as one of the genes predicting breast cancer to lung metastasis with the greatest frequency." (PMID 33196458, 2020). "Further studies found that IL-1β promoted obesity-driven breast cancer angiogenesis and progression via the upregulation of angiopoietin-like 4 (ANGPTL4) in adipocytes." (PMID 32630445, 2020). "Considering the hundreds of cytokines and growth factors in ACM, this 50% of effect makes TGF-β2 one of the major factors derived by astrocytes that regulate the expression of ANGPTL4 in brain-metastatic breast cancer cells." (PMID 31602400, 2019). "Levels of ANGPTL4 are correlated with inflammatory markers including C-reactive protein and IL-1β in serum from patients with type 2 diabetes and breast cancer." (PMID 29563332, 2018). "It has been demonstrated that ANGPTL4 was expressed at higher levels in the blood of breast cancer patients and high expression of ANGPTL4 correlated with a minor disease-free survival of breast cancer young patients." (PMID 29389861, 2018). "ANGPTL4 has only been described in relation to breast cancer metastasis, but its pro-metastatic role was largely related to distant lung or brain metastases with little mention of bone metastatic disease." (PMID 28458654, 2017). "This suggests an interesting link since Angptl4 has been described to promote breast cancer cell invasion and metastasis to the lung in vitro and in vivo, respectively." (PMID 29163362, 2017). "In particular, it has been shown to induce an increase in human ANGPTL4 levels in breast cancer cells, by activating SMAD transcription factors, ultimately favoring the transendothelial migration of tumor cells through disruption of endothelial cell junctions." (PMID 28182091, 2017). "Lung metastasis from ANGPTL4-knockdown breast cancer cells following mammary fat pad implantation were also significantly reduced compared to mice bearing control tumors." (PMID 27706047, 2016). "For example, conditioned media from breast cancer cells stably transfected with an ANGPTL4 expression vector inhibited EC–EC interactions as measured by transendothelial electrical resistance and breast cancer invasion assays." (PMID 27706047, 2016). "Clinically, ANGPTL4 is expressed at increased levels in the primary breast cancers of women with lung metastases." (PMID 27706047, 2016). "The role of ANGPTL4 in breast cancer metastasis to both lung and brain makes it an interesting potential druggable target." (PMID 25999348, 2015). "ANGPTL4 plays a critical role in cancer growth and progression and specifically contributes to breast cancer metastasis by protecting endothelial cells from apoptosis promoting angiogenesis, and facilitating cell migration." (PMID 25999348, 2015). "Human breast cancer cell invasion into a three dimensional Matrigel matrix is critically dependent on Angptl4 expression." (PMID 26512722, 2015). "For breast cancer, angiopoietin-like 4 (ANGPTL4) and L1 cell adhesion molecule (L1CAM) are the two important molecules that mediate vascular metastasis of hypoxic breast cancer cells to the lungs." (PMID 23241400, 2012). "More recently, Padua and colleagues reported that ANGPTL4 mediated breast cancer cell metastasis to the lung in a transforming growth factor-β-dependent manner by altering endothelial integrity." (PMID 20454689, 2010).